MALAT1 (metastasis associated lung adenocarcinoma transcript 1)
Diseases named in the same sentence as MALAT1 in open-access papers (continued):
Sharing a sentence is not in itself a finding about the gene and the disease.
colorectal cancer (continued). "MALAT1 also has been reported interaction with miR-218 decreasing E-cadherin and promoting oxaliplatin-based chemotherapy resistance in colorectal cancer through EZH2-mediating H3K27-me3." (PMID 32708561, 2020). "The specific lncRNA was valuable in predicting the prognosis of colorectal cancer by investigating the correlations between MALAT1 and miR-106b-5p." (PMID 31792655, 2020). "In support of this explanation, translation of this micropeptide from lncRNA MALAT1 has been previously reported in several ribosome-profiling experiments using human colorectal cancer cells HCT116 and human embryonic kidney HEK293 cells." (PMID 32867128, 2020). "Another report has showed that MALAT1 is overexpressed in colorectal cancers and that SNV rs1194338 mapping to its promoter region is significantly associated with a decreased risk of colorectal cancer." (PMID 32523949, 2020). "lncRNA MALAT1 expression was increased in chemoresistant gastric cancer cells and colorectal cancer cells, and was positively related with autophagy activity." (PMID 33050642, 2020). "In human colorectal cancer cells and tissues, MALAT1 expression positively correlates with YAP1, negatively correlates with miR-126-5p and miR-20b-5p expression, and predicts poor patient prognosis." (PMID 32174966, 2020). "Long non-coding RNA Malat1 activated autophagy and promoted cell proliferation, yet inhibited apoptosis by sponging miR-101 in colorectal cancer cells." (PMID 31372165, 2019). "First, the expression level of Malat1 in 96 pairs of colorectal cancer tissues and four cell lines was detected by qRT-PCR." (PMID 31372165, 2019). "Long non-coding RNA Malat1 has been widely identified as an oncogene which shows a significant relationship with tumorigenesis in colorectal cancer (CRC)." (PMID 31372165, 2019). "In this study, significantly increased Malat1 expression and autophagy activity were found in colorectal cancer tissues compared with the adjacent normal tissues." (PMID 31372165, 2019). "Chronic oxymatrine treatment induced chemotherapy resistance and epithelial-mesenchymal transition through targeting MALAT1 in colorectal cancer cells." (PMID 31143372, 2019). "We have also shown progressive expression of MALAT1 across the different stages of colorectal cancer and were able to correlate the stages with the progression of CRC." (PMID 30189670, 2018). "The regulatory function of lncRNA MALAT1 / miR-145 / SOX9 axis was revealed in colorectal cancer based on bioinformatics analysis." (PMID 30285605, 2018). "In this present study, we noted that significantly up-regulated MALAT1 expression was observed in colorectal cancer tissues and cells." (PMID 30285605, 2018). "Taken together, to make an investigation on the critical function and mechanism of MALAT1/miR-145/SOX9 in colorectal cancer, the expression and the correlation among MALAT1, miR-145 and SOX9 were determined." (PMID 30285605, 2018). "More recently, MALAT1 was identified to have diverse effect on carcinogenesis, such as cell proliferation and apoptosis in colorectal cancer, gastric cancer and pancreatic cancer." (PMID 29290978, 2017). "Our earlier findings indicate that the long non-coding RNA MALAT1 promotes colorectal cancer (CRC) cell proliferation, invasion and metastasis in vitro and in vivo by increasing expression of AKAP-9." (PMID 26887056, 2016). "It was reported that resveratrol decreased nuclear localization of β-catenin thus attenuated β-catenin signaling after silencing MALAT1 in colorectal cancer cells." (PMID 27015363, 2016). "The overexpression of MALAT1 has also been described in gastric cancer, prostate cancer and colorectal cancer." (PMID 27793008, 2016). "HOTAIR and MALAT1 have also been demonstrated to be involved in breast and colorectal cancer metastasis." (PMID 25428914, 2015). "MALAT1 upregulation has been reported to promote colorectal cancer development via its target protein A-kinase anchor protein." (PMID 26552600, 2015).
colorectal cancer (continued). "ER stress-induced activation of PERK upregulates lncRNAs such as Golgin A2 pseudogene 10 (GOLGA2P10), which modulates Bcl-2 protein levels to protect hepatocellular carcinoma cells from apoptosis, and MALAT1, which enhances colorectal cancer cell migration following exposure to thapsigargin." (PMID 40429961, 2025). "Accumulating evidence indicates that MALAT1 serves as a pivotal determinant in diagnosing metastatic potential across various malignancies, exhibiting notably elevated expression in recurrent colorectal cancer and metastatic lesions." (PMID 39319867, 2025). "Treating human colorectal carcinoma cells with each of the TBMs reduced MALAT1 levels by ~20–60%." (PMID 41226238, 2025). "Similarly, MALAT-1 is also upregulated in colorectal cancers and promotes the proliferation of colorectal cancer cells." (PMID 38473243, 2024). "Additionally, MALAT1 serves as a miR-26a-5p sponge, modulating Smad1 and thus influencing colorectal cancer progression by orchestrating autophagy." (PMID 39323624, 2024). "Human colorectal carcinoma (HCT116) cells transfected with LNAs have 2-fold less MALAT1 and MENβ." (PMID 38338910, 2024). "MALAT1 is dysregulated in various cancer types, including colorectal cancer." (PMID 37325561, 2023). "In human colorectal cancers, MALAT1 transcripts were downregulated relative to normal tissue." (PMID 37325561, 2023). "Furthermore, liver and lung metastases of colorectal cancer are advanced by exosomal MALAT1 in vivo." (PMID 35055115, 2022). "Below, we summarized the overview function of MALAT1 in colorectal cancer." (PMID 35305641, 2022). "Since MALAT1 is known to sponge miR-26b to promote invasion and metastasis of colorectal cancer, we expected that MALAT1 might also sponge miR-26b in BC, and that miR-26b targets and down-regulates HMGA2." (PMID 34419065, 2021). "Similarly, MALAT1 is also upregulated in high grade colorectal cancers and its expression correlates with poor prognosis." (PMID 34307387, 2021). "Consistently, lncRNA MALAT1 also plays a pro-oncogenic role in ovarian cancer, osteosarcoma, acute lymphoblastic leukemia, and colorectal cancer." (PMID 35111811, 2021). "The influence of PVT1 and MALAT1 variants on colorectal cancer (CRC) susceptibility and their impact on PVT1/miRNA-186/epithelial-mesenchymal transition (EMT) and MALAT1/miRNA-101/EMT axes in CRC are unknown." (PMID 34200314, 2021). "In human colorectal cancer cells, MALAT1 expression is up-regulated by YAP1, sponges miR-126-5p and miR-20b-5p, and thereby up-regulates the expression of tumor cell stemness proteins such as Oct4 and Nanog and metastasis-associated molecules such as VEGF, SNAI2, and TWIST." (PMID 32174966, 2020). "Moreover, colorectal cancer patients with a higher level of MALAT1 in primary tumors had poor prognosis." (PMID 31792655, 2020). "In colorectal cancer, MALAT1 promoted autophagy activity by acting as a ceRNA with miR-101." (PMID 33050642, 2020). "Emerging data have indicated that MALAT1 may regulate autophagosome maturation through a ceRNA mechanism, contributing to chemoresistance in gastric and colorectal cancers." (PMID 33050642, 2020). "Importantly, EZH2 has been reported to be related to 3′-end of MALAT1 and down-regulate the expression of E-cadherin in colorectal cancer." (PMID 31174563, 2019). "Furthermore, the CCK-8 assay and flow cytometry (FCM) were performed to detect the role of autophagy activated by Malat1 in colorectal cancer cell lines." (PMID 31372165, 2019). "Furthermore, chemosensitivity studies demonstrated that the level of MALAT1 in colorectal cancer cells correlates to their resistance to oxaliplatin." (PMID 35582574, 2019). "Recently, it has been observed that MALAT1 has a metastatic role in colorectal cancer." (PMID 32099603, 2019). "Moreover, autophagy activation and cell proliferation were significantly facilitated by Malat1 in colorectal cancer cells, while apoptosis decreased." (PMID 31372165, 2019).
colorectal cancer (continued). "Additionally, we have observed an increase in MALAT1 expression in different stages of colorectal cancer." (PMID 30189670, 2018). "Interestingly, lncRNA MALAT1 stained very well with respect to the progression of colorectal cancer." (PMID 30189670, 2018). "The effect of MALAT1 on colorectal cancer in vivo was constructed by xenograft model." (PMID 30285605, 2018). "Down-regulated MALAT1 could induce resistance of G1 phase in cell cycle, and facilitation of colorectal cancer cell apoptosis." (PMID 30285605, 2018). "In colorectal cancer, MALAT1 could also bind to splicing factor proline and glutamine rich (SFPQ), thus increasing cell proliferation and migration." (PMID 30131454, 2018). "With the enhancement of kinase (PRKA) anchor protein 9 (AKAP-9) expression, MALAT-1 could accelerate cell proliferation, migration and invasion in vitro, which implied that MALAT1 acted as a potential role in the progression of colorectal cancer." (PMID 30285605, 2018). "Moreover, over-expression of MALAT1 enhanced the cell growth of colorectal cancer cells, whereas miR-145 showed the opposite effect through repressing SOX9 expression." (PMID 30285605, 2018). "In consideration of structure and cytoplasmic distribution of MALAT1 in colorectal cancer cell, we hypothesized that MALAT1 may function as a competing endogenous RNA to miR-145." (PMID 30285605, 2018). "Furthermore, gene expression profiling analysis revealed overexpression of MALAT1 mRNA in colorectal cancer tissue compared with normal controls." (PMID 29190941, 2017). "Many researches also indicated that MALAT1 is linked to other cancer types or diseases as a negative prognosis factor, such as glioma, pancreatic cancer, colorectal cancer, etc.." (PMID 28253859, 2017). "In colorectal cancer (CRC), the MALAT1 level is highly expressed in tumor and is associated closely with CRC invasion and metastasis; besides, MALAT1 could motivate CRC cell proliferation, migration and invasion through PRKA kinase anchor protein 9 (AKAP-9)." (PMID 29190941, 2017). "MALAT-1 is overexpressed in multiple types of human malignancies, including hepatocellular cell carcinoma, lung adenocarcinoma, endometrial stromal sarcoma, and colorectal cancer." (PMID 26989678, 2016). "Examples include HOTAIR in colorectal cancer and MALAT1 in non-small cell lung cancer." (PMID 25428914, 2015). "In colorectal cancer, MALAT1 could disturb the stability of SFPQ/PTBP2 complex, and promote cell proliferation and migration." (PMID 26522444, 2015). "Additionally, an oncogenic role has also been proposed for MALAT1 in colorectal carcinoma." (PMID 36902227, 2023). "However, the mechanism through which MALAT1 repressed apoptosis in colorectal cancer remains unclear." (PMID 33414433, 2021). "Nevertheless, the function of MALAT1 in colorectal cancer (CRC) remains largely unknown." (PMID 33344634, 2020). "Colorectal cancer growth and metastasis could be promoted by the release of oncogene PTBP2 from the SFPQ/PTBP2 complex, which is achieved by the affinity between human metastasis-associated lung adenocarcinoma transcript 1 (lncRNA MALAT1) and SFPQ." (PMID 32429086, 2020). "Moreover, another study showed that the down‐regulation of MALAT1 could suppress tumorigenesis through modulating miR‐20b‐5p/Oct4 network in colorectal cancer." (PMID 32383354, 2020). "Nonetheless, whether Malat1 participates in the autophagy of colorectal cancer remains unclear." (PMID 31372165, 2019). "Additionally, it has been demonstrated that the lncRNA MALAT1 may be considered as a potential prognostic and therapeutic target of colorectal cancer patients as it can fulfill a chemoresistant function in colorectal cancer." (PMID 29986541, 2018). "We could see that in si-MALAT1 group, the expression of miR-145 was higher and SOX9 was lower than NC group, further verifying the knockdown of MALAT1 inhibited the growth of colorectal cancer in vivo by up-regulating miR-145 and down-regulating SOX9 (P < 0.01)." (PMID 30285605, 2018).
colorectal cancer (continued). "Besides, over-expression of MALAT-1 was found in colorectal cancer." (PMID 30285605, 2018). "MALAT1, also known as LINC00047 (ENSG00000251562) is a lncRNA involved in triple-negative breast cancer, B-cell lymphoma, colorectal cancer and multiple myeloma." (PMID 40863726, 2025). "For instance, MALAT1 increases HMGB1 levels in hepatic injury, colorectal cancer, and multiple myeloma, often acting as a competitive endogenous RNA (ceRNA) for miRNAs that target HMGB1." (PMID 40429961, 2025). "Several studies reported that certain lncRNAs contribute to the progression of colorectal cancer, such as HOTAIR, MALAT-1, and CCAT1/CCAT2." (PMID 38473243, 2024). "MALAT1 can bind to SFPQ, resulting in the release of PTBP2 from the SFPQ/PTBP2 complex and promoting the growth and metastasis of colorectal cancer cells." (PMID 39532842, 2024). "In the context of colorectal cancer, YAP1-induced MALAT1 is currently recognised as an effective motivator of EMT and angiogenesis, facilitated through its sponge-like properties for miR-126-5p." (PMID 39323624, 2024). "And PTBP2 be released by MALAT1 from the SFPQ/PTBP2 complex, thereby facilitating tumor growth and migration in colorectal cancer cells." (PMID 39830506, 2024). "L15 and PS-L15 can displace the A-rich tract and METTL16 from the MALAT1 and MENβ triple helices, leading to a 2-fold reduction in MALAT1 and MENβ levels in LNA-transfected human colorectal carcinoma (HCT116) cells." (PMID 38338910, 2024). "We found that TSGs (e.g., DKK1 and GAS5) in colorectal cancer with hypermethylated promotors were re-activated and two oncogenes (i.e., EREG and MALAT1) were down-regulated upon 5-AZA-CdR treatment." (PMID 36882403, 2023). "MALAT1 has been ensured to be positively regulated by JMJD2C through modification of histone methylation, and works to enhance metastasis of colorectal cancer cells." (PMID 35046387, 2022). "It was reported that long non-coding (Lnc) MALAT1 was upregulated in colorectal cancer tissues and RES inhibits invasion and metastasis via Lnc MALAT1 mediated Wnt/β-catenin signal pathway." (PMID 33937049, 2021). "In patients with high MALAT1 expression, it was found that MALAT1 binds EZH2 to the CDH1 promoter and inhibits miR-218 during oxaliplatin treatment, indirectly promoting EMT, metastasis, and chemoresistance of colorectal cancer cells." (PMID 34199840, 2021). "We first evaluated expression levels of several lncRNAs in eight excised liver metastases from primary colorectal cancers and found significantly upregulated lncRNAs HOTAIR and MALAT1 along with significantly downregulated LOC285194." (PMID 34307387, 2021). "For instance, lncRNA MALAT1 overexpression promotes endothelial cell formation and HIF-1 α protein expression, and participates in the occurrence and development of colorectal cancer by promoting the colorectal cancer cells mediated angiogenesis." (PMID 34234865, 2021). "In particular, MALAT1 can activate EZH2 pathway in aggressive renal cell carcinoma, colorectal cancers and osteosarcoma 22-24." (PMID 34234858, 2021). "Further work is required to validate the potential relationship between MALAT1 and ATG4D in colorectal cancers." (PMID 33050642, 2020). "MALAT1 binds to EZH2 and suppresses E-cadherin expression and promotes oxaliplatin-induced EMT and colorectal cancer cell resistance to oxaliplatin." (PMID 32174966, 2020). "By experimental verification, MALAT1 and SOX9 were expressed in a high percentage of colorectal cancer tumors and cells, while miR-145 was in a low expression." (PMID 30285605, 2018). "By analyzing the expression of 17 lncRNAs and 31 circRNAs in biopsies and serum exosomes from colorectal cancer (CRC) patients through qRT-PCR, we detected CCAT1, CCAT2, HOTAIR, and UCA1 upregulation and CDR1AS, MALAT1, and TUG1 downregulation in biopsies." (PMID 30195762, 2018).
colorectal cancer (continued). "For the study, we determine the potential biomarkers and uncover the regulatory mechanisms of lncRNA MALAT1 / miR-145 / SOX9 axis on the abilities of cell growth and cell metastasis of colorectal cancer." (PMID 30285605, 2018). "In addition, MALAT1 may also promote colorectal cancer development by directly targeting AKAP9." (PMID 27458156, 2016). "Nowadays, biological experiments have further linked mutations and dysregulations of some lncRNAs with the development and progression of colorectal cancer, such as HOTAIR, KCNQ1OT1, and MALAT1 in our training samples." (PMID 26061969, 2015). "MALAT-1, HOTAIR, PVT-1 and CCAT1-L are up-regulated in colorectal cancer tissue while ncRAN is down-regulated." (PMID 25119862, 2014). "MALAT1 could also upregulate FUT4 expression and enhances fucoidan glycosylation and in laboratory studies, MALAT1 triggers the activation of the PI3K/AKT/mTOR pathway, thereby promoting colorectal cancer cell invasiveness." (PMID 39830506, 2024). "MALAT1 also increases the transcriptional activity of YAP1, which can alter the HR as well as the non–homologous end joining (NHEJ) pathway, to confer radioresistance to colorectal cancer cells." (PMID 37812088, 2023). "Moreover, YAP1-induced MALAT1 facilitates epithelial-mesenchymal transition (EMT) and angiogenesis by sponging miR-126-5p in colorectal cancer." (PMID 36813772, 2023). "The aberrations found in this study (losses of TSC2, COL1A1, NOTCH1, MIR4673 and GNAS, and gains of MALAT1 and TALAM1) may serve as candidate biomarkers for early detection of colorectal cancer onset." (PMID 35887000, 2022). "Exosomal MALAT1 and UCA1 serve as pro-metastatic factors in colorectal cancer." (PMID 35055115, 2022). "Curcumin combined with si-MALAT1 could significantly reduce its expression and inhibit the cell activity, migration, and invasion of SW480 (colorectal cancer cell)." (PMID 36291546, 2022). "Our study identified that MALAT1 promotes colorectal cancer oxaliplatin resistance by reducing the miR-200s expression, and ZJW may reverse chemoresistance by inhibiting the expression of MALAT1 and regulating the miR-200s/JNK pathway." (PMID 36248422, 2022). "Among the differential lncRNAs and genes which could establish lncRNA-miRNA-mRNA regulatory axis, MALAT1 and SOX9 were found to be close to colorectal cancer progress through references." (PMID 30285605, 2018). "Therefore, MALAT1, miR-145 and SOX9 are indicated to be novel promising candidates for developing effective therapeutic strategies for colorectal cancer." (PMID 30285605, 2018). "MALAT1 mediated-Wnt/β-catenin regulation has reported in oral squamous, esophageal squamous cells and colorectal cancer but did not report in gastric cancer yet." (PMID 28077118, 2017). "For example, In the investigation of colorectal cancer (CRC), MALAT1 could bind to SFPQ, thus releasing PTBP2 from the SFPQ/PTBP2 complex and the interaction between MALAT1 and SFPQ could be a novel therapeutic target for CRC35." (PMID 28623317, 2017). "XIST, MALAT1, H19, and KCNQ1OT1 were ranked in the top four prediction list of colorectal cancer." (PMID 26278472, 2015). "Given that JMJD2C promotes colorectal cancer (CRC) metastasis via histone methylation of metastasis-related lung adenocarcinoma transcript 1 (MALAT1), it is unclear whether and how JMJD2C-mediated downstream involving MALAT1 functions in NSCLC." (PMID 35046387, 2022). "MALAT1 is significantly more highly expressed in non–small cell lung carcinoma (NSCLC) patients and induces invasion, migration, and tumor growth in many cancer types, including lung cancer, uterine endometrial stromal sarcoma, colorectal cancer, and hepatocellular carcinoma." (PMID 28077118, 2017). "Moreover, the lncRNA MALAT1 could mediate cisplatin resistance via the miR-101-3p/VEGF-C pathway in bladder cancer and promote cell proliferation and inhibit apoptosis by sponging miR-101 in colorectal cancer." (PMID 34222227, 2021).